IGHV3-35 (immunoglobulin heavy variable 3-35 (non-functional))
Description:
Probable non-functional open reading frame (ORF) of V region of the variable domain of immunoglobulin heavy chains. Non-functional ORF generally cannot participate in the synthesis of a productive immunoglobulin chain due to altered V- (D)-J or switch recombination and/or splicing site (at mRNA level) and/or conserved amino acid change (protein level). Immunoglobulins, also known as antibodies, are membrane-bound or secreted glycoproteins produced by B lymphocytes. In the recognition phase of humoral immunity, the membrane-bound immunoglobulins serve as receptors which, upon binding of a specific antigen, trigger the clonal expansion and differentiation of B lymphocytes into immunoglobulins-secreting plasma cells. Secreted immunoglobulins mediate the effector phase of humoral immunity, which results in the elimination of bound antigens. The antigen binding site is formed by the variable domain of one heavy chain, together with that of its associated light chain. Thus, each immunoglobulin has two antigen binding sites with remarkable affinity for a particular antigen. The variable domains are assembled by a process called V-(D)-J rearrangement and can then be subjected to somatic hypermutations which, after exposure to antigen and selection, allow affinity maturation for a particular antigen.
Synonyms: IGHV335; VH
Gene: Immunoglobulin variable (V) gene on chromosome 14 (106,389,392 to 106,389,858, reverse strand). Ensembl gene ENSG00000211957.
Subcellular location: Secreted; Cell membrane
Gene Ontology:
Molecular function: antigen binding
Biological process: immunoglobulin mediated immune response
Cellular component: extracellular region; plasma membrane
Homologues: Paralogues in human: IGHV3-16 (91% identical), IGHV3-23 (84% identical), IGHV3-74 (84% identical), IGHV3-48 (82% identical), IGHV3-64 (82% identical), IGHV3-66 (82% identical), IGHV3-64D (81% identical), IGHV3OR16-13 (81% identical), IGHV3-11 (80% identical), IGHV3-20 (80% identical), IGHV3-21 (80% identical), IGHV3-43 (80% identical), and 65 more.
Diseases named in the same sentence as IGHV3-35 in open-access papers:
IGHV3-35 is named in the same sentence as 2 diseases in open-access papers, as found by Europe PMC text mining. Sharing a sentence is not in itself a finding about the gene and the disease. The quoted sentences say what the papers report.
gingivitis (1 paper, 2025). A disorder involving inflammation of the gums; may affect surrounding and supporting structures of the teeth. "The proteins CD55, GBP6, IGHV3-35, and IGKV1-6 are significant markers in the context of the host response to bacterial infections, particularly in relation to gingivitis and treatment outcomes." (PMID 41156831, 2025).
IGHV3-35 also shares sentences with these, for which no sentence is quoted: bacterial infections (1 paper).